ENSG00000268434 (novel protein)
Gene: Protein-coding gene on chromosome 19 (45,779,437 to 45,785,973, reverse strand). Ensembl gene ENSG00000268434.
Genetic constraint (gnomAD): Loss-of-function variants: 8 observed, 14.19 expected, observed/expected ratio (o/e) 0.56, 90% interval 0.33 to 1.02. Missense variants: 150 observed, 139.08 expected, observed/expected ratio (o/e) 1.08, 90% interval 0.94 to 1.24. Synonymous variants: 72 observed, 56.66 expected, observed/expected ratio (o/e) 1.27, 90% interval 1.05 to 1.55.